PCSK1N (proprotein convertase subtilisin/kexin type 1 inhibitor)
Description:
May function in the control of the neuroendocrine secretory pathway. Proposed be a specific endogenous inhibitor of PCSK1. ProSAAS and Big PEN-LEN, both containing the C-terminal inhibitory domain, but not the further processed peptides reduce PCSK1 activity in the endoplasmic reticulum and Golgi. It reduces the activity of the 84 kDa form but not the autocatalytically derived 66 kDa form of PCSK1. Subsequent processing of proSAAS may eliminate the inhibition. Slows down convertase-mediated processing of proopiomelanocortin and proenkephalin. May control the intracellular timing of PCSK1 rather than its total level of activity (By similarity). [Big LEN]: Endogenous ligand for GPR171. Neuropeptide involved in the regulation of feeding. [PEN]: Endogenous ligand for GPR83. Neuropeptide involved in the regulation of feeding.
Synonyms: SAAS; SgVIII; SCG8; proSAAS; PEN; BigLEN
Tractability: Antibody: UniProt places it where antibodies can reach, with medium confidence; UniProt predicts a signal peptide or a membrane-spanning region; its Gene Ontology location is reachable by antibodies, with medium confidence. PROTAC: its protein half-life has been measured.
Gene: Protein-coding gene on chromosome X (48,831,088 to 48,835,632, reverse strand). Ensembl gene ENSG00000102109.
Subcellular location: Secreted; Golgi apparatus, trans-Golgi network
Subcellular location (Human Protein Atlas): Vesicles; Predicted to be secreted
Gene Ontology:
Molecular function: endopeptidase inhibitor activity; protein-containing complex destabilizing activity; signaling receptor binding; serine-type endopeptidase inhibitor activity
Biological process: detoxification; nervous system process
Cellular component: extracellular region; Golgi apparatus; secretory granule; trans-Golgi network
Homologues: Orthologues: chimpanzee PCSK1N (100% identical), macaque PCSK1N (98% identical), dog PCSK1N (88% identical), rat Pcsk1n (84% identical), guinea pig PCSK1N (83% identical), mouse Pcsk1n (83% identical), rabbit PCSK1N (80% identical), pig PCSK1N (77% identical).
Diseases named in the same sentence as PCSK1N in open-access papers:
PCSK1N is named in the same sentence as 49 diseases in open-access papers, as found by Europe PMC text mining. Sharing a sentence is not in itself a finding about the gene and the disease. The quoted sentences say what the papers report.
Obesity (8 papers, 2011 to 2022). Accumulation of substantial excess body fat. "As a natural endogenous inhibitor of Pcsk1 (prohormone converting enzyme 1), Pcsk1n slows down the mediating effect of hormone converting enzyme and promotes food intake and obesity, and Pcsk1 gene mutations are common in the obese human population." (PMID 35525962, 2022). "A polymorphism in the PPARGC1A gene is related to obesity and type 2 diabetes, while the down-regulation of PCSK1N gene expression is also associated with obesity." (PMID 32485856, 2020). "ACP cystic fluid caused growth retardation and an increased obesity index in mice, affected the expression of the Npy, Fgfr2, Rnpc3, Sst, and Pcsk1n genes that regulate growth and energy metabolism in hypothalamic neurons, and enhanced the cellular interaction of Agrp–Mc3r." (PMID 35525962, 2022). "The high expression of proSAAS encoded by Pcsk1n causes obesity and diabetes in mice." (PMID 35525962, 2022). "Likewise, the other two DEGs identified in the present study—PPARGC1A (peroxisome proliferator-activated receptor-γ co-activator-1alpha) and PCSK1N (proprotein convertase subtilisin/kexin type 1 inhibitor)—have been associated with obesity in humans." (PMID 32485856, 2020). "And up-regulated genes-NAMPT, TLR9, PTGS2, HBD, and PCSK1N might be associated with obesity risk." (PMID 29132311, 2017). "DEGs of NAMPT, TLR9, PTGS2, HBD, and PCSK1N might be associated with obesity." (PMID 29132311, 2017). "Thus, downregulation of PCSK1N may result in obesity, which is a risk factor for RCC." (PMID 30941304, 2019). "In addition, PCSK1N gene might also be associated with obesity." (PMID 29132311, 2017). "Overexpression of PCSK1N in mice resulted in obesity and diabetes and PCSK1N-derived peptides promote food intake." (PMID 23526982, 2013). "The related genes of obesity (ADIPOQ, GCG, PCSK1N, TFAP2A, and PYY) were also found to play significant roles in the occurrence of some types of cancer (BRCA, COAD, and UCEC)." (PMID 33299884, 2020). "In addition, five related genes of obesity (ADIPOQ, GCG, PCSK1N, TFAP2A, and PYY) were distributed in the top 25 over/underexpressed genes of cancer tissues." (PMID 33299884, 2020).
Alzheimer disease (7 papers, 2019 to 2024). A progressive, neurodegenerative disease characterized by loss of function and death of nerve cells in several areas of the brain leading to loss of cognitive function such as memory and language. "The upregulated genes include Avp, associated with schizophrenia and depression; Hcrt, related to anxiety, depression, and pain; and Pcsk1n, which is predictive of Alzheimer’s disease via association with the amyloid antiaggregant protein, proSAAS." (PMID 31912136, 2020). "PCSK1N is also considered as a potential target for the treatment of Alzheimer’s disease due to its anti-aggregant properties." (PMID 38017352, 2024). "The most strongly downregulated gene, Pcsk1n (L2FC -1.25, FDR < 3E-5), encodes proSAAS, a secreted chaperone that has anti-aggregation activity and is found associated with protein aggregates in brains of Alzheimer’s disease (AD) patients and an AD mouse model." (PMID 35960762, 2022). "Another protein, PCSK1N, also called proSAAS, an inhibitor of prohormone convertase 1 (PC1) activity produced by neuroendocrine cells, has been proven to be a biomarker for many neurological disorders, including Alzheimer’s disease (AD), Pick’s disease, and the Parkinsonism-dementia complex." (PMID 36891236, 2023).
dementia (4 papers, 2019 to 2023). Loss of intellectual abilities interfering with an individual's social and occupational functions. "It has been identified as a cerebrospinal fluid candidate biomarker for AD and/or dementia, and a recent transcriptomic analysis showed that PCSK1N expression increased during AD progression." (PMID 36613555, 2022).
diabetes (3 papers, 2013 to 2024). "By inactivating the proconvertase, the PCKS1 inhibitor (PCSK1N) regulates neuroendocrine secretory activity and has been associated with the development of diabetes." (PMID 38017352, 2024).
adenoma (2 papers, 2020 to 2022). A neoplasm arising from the epithelium. "Moreover, transcriptome and proteome analysis comparing gene expression between SCAs and functioning corticotrope adenomas identified alterations in endoplasmic reticulum protein processing and in ACTH synthesis such as the overexpression of PCSK1N, an indirect inhibitor of ACTH maturation." (PMID 35743266, 2022). "Moreover, we demonstrate that protein level PCSK1N, a well described inhibitor of PCSK1-mediated processing of POMC, was significantly increased in SCA, suggesting an additional mechanism responsible for the impaired POMC processing in the silent adenomas." (PMID 33066652, 2020).
type 2 diabetes (2 papers, 2020 to 2025). "PCSK1N regulates neuropeptide processing essential for energy homeostasis and appetite regulation, and its expression has been linked tobody mass index (BMI), age, and type 2 diabetes, while contradictory findings were also reported." (PMID 40986521, 2025).
cognitive decline (1 paper, 2020). "Low CSF levels of all biomarker candidates, except PCSK1N, were associated with more pronounced cognitive decline." (PMID 32552841, 2020). "Low CSF levels of all biomarker candidates, except PCSK1N, were associated with more pronounced cognitive decline (0.37 < r < 0.56, all p < 0.01)." (PMID 32552841, 2020).
cyst (1 paper, 2022). A sac-like closed membranous structure that may be empty or contain fluid or amorphous material. "At the same time, the Npy and Pcsk1n genes were significantly highly expressed in ARC neurons in the cyst fluid group." (PMID 35525962, 2022).
embryonic carcinoma (1 paper, 2013). "To further test whether Gaa, Isl1, Kif1b, Mtmr2, Pcsk1n, and Snca, are regulated by Pax6, we performed co-transfection studies in cultured P19 embryonic carcinoma and αTN4-1 lens epithelial cells." (PMID 23342162, 2013).
Fanconi anemia (1 paper, 2025). Fanconi anemia (FA) is a hereditary DNA repair disorder characterized by progressive pancytopenia with bone marrow failure, variable congenital malformations and predisposition to develop hematological or solid tumors. "PCSK1N was enriched in the cytosolic DNA‐sensing pathway, Th17 cell differentiation, and phagosome pathway, while VGF was associated with the Fanconi anemia pathway, DNA replication, and cell cycle pathway." (PMID 40600620, 2025).
gastric adenocarcinoma (1 paper, 2024). "Western blotting also showed high expression of SPINK4, TTR, PCSK1N, CHGA and GHRL in gastric adenocarcinoma cell lines, with GHRL showing the most significant increase (p < 0.05)." (PMID 38752750, 2024).
Lymphatic Metastasis (1 paper, 2025). Transfer of a neoplasm from its primary site to lymph nodes or to distant parts of the body by way of the lymphatic system. "Only 6 genes, namely CHGA, CHGB, PCSK2, PCSK1N, DLGAP1 and DLGAP3 were down-Regulated in the lymphatic metastasis group." (PMID 41431044, 2025).
neuroblastoma (1 paper, 2025). Neuroblastoma (NB) is the most common solid, extracranial childhood tumor. "Notably, CKB and PCSK1N emerged as potential drivers of tumor progression, highlighting their promise as therapeutic targets in MYCN‐amplified neuroblastoma." (PMID 40600620, 2025).
renal angiomyolipoma (1 paper, 2023). "After applying Pearson analysis, we identified five proteins (out of the 34 intersected DE proteins) positively correlated with the maximum renal angiomyolipoma (p < 0.05), namely, PCSK1N, PMEL, HK1, GOT2 and SPTBN2." (PMID 36891236, 2023).
Spinocerebellar ataxia type 43 (1 paper, 2023). "Even the neuropeptide activator Pcsk1 and its inhibitor Pcsk1n, as well as neuropeptide inactivators like Mme (which is responsible for Spinocerebellar Ataxia type 43) and Ecel1 were upregulated." (PMID 37830614, 2023).
tumor (9 papers, 2019 to 2025). "PCSK1N is linked to the cytosolic DNA‐sensing pathway and Th17 cell differentiation, suggesting a dual role in innate immune responses and tumor microenvironment modulation." (PMID 40600620, 2025). "The modest but significant positive correlations suggest that CKB and PCSK1N expression levels tend to increase in MYCN‐high tumor cells, possibly placing them under MYCN regulatory control or within the same oncogenic program." (PMID 40600620, 2025). "In particular, the identification of CKB and PCSK1N suggests their potential role in driving tumor progression, making them promising targets for novel treatments in MYCN‐driven NB." (PMID 40600620, 2025). "Two genes were upregulated (SERHL2 and SPNS2) in low cytoplasmic CAIX tumours, while one gene (PCSK1N) was downregulated, as shown in the volcano plot and MA plot (respectively)." (PMID 39660488, 2024). "Involvement of PCSK1N in metabolic and immune‐related pathways may indicate its role in modulating tumor microenvironment, potentially aiding tumor progression and immune evasion in MYCN‐amplified." (PMID 40600620, 2025). "We found a high correlation of APOE, LGALS1, and PCSK1N, which were primarily expressed in SLS tumor cells, with macrophage frequency/activity in SLS-dominant tumors." (PMID 36028490, 2022). "The profiled tumor cells expressed most general PNEC markers (e.g. SCG5, CHGB, SCG2, PCSK1N, CHGA, SCG3) indicating retention of PNEC identity." (PMID 36469459, 2022). "Furthermore, the positive relationship of PCSK1N with activated NK and CD4 memory T cells reinforces its potential role in fostering anti‐tumor immunity." (PMID 40600620, 2025). "Notably, we identify ANGPT2, PCSK1N, and GPX3 as key subtype-specific biomarkers, with ANGPT2 driving tumor progression in C1 and emerging as a potential therapeutic target." (PMID 41400463, 2025). "Comparison of expression profiles of ET (≤40 years) and LT (≥55 years) yielded few genes that are unique between the two groups, 7 genes B4GALNT1, S100P, KLK4, HIST3H2A, DRD4, PCSK1N, and BAPX1 were significantly overexpressed in early-onset tumours compared to late-onset tumours." (PMID 31292488, 2019).
cancer (4 papers, 2019 to 2022). A tumor composed of atypical neoplastic, often pleomorphic cells that invade other tissues. "When the DEGs were further compared across four cancer types, we found five coregulated DEGs (upregulated DEGs: PCSK1N, CAMK2B, RUNDC3A and SNAP25; downregulated DEG: DPT) among four NECs." (PMID 35752613, 2022).
neurodegenerative disease (3 papers, 2020 to 2022). A disorder of the central nervous system characterized by gradual and progressive loss of neural tissue and neurologic function. "PCSK1N has an association with various neurodegenerative diseases, widely expressed in neurons throughout the brain." (PMID 35203526, 2022).
neurological disorders (2 papers, 2020 to 2023). "Third, PCSK1N, an inhibitor of prohormone convertase (PC) activity, has also been proposed as a CSF biomarker candidate for several neurological disorders." (PMID 32552841, 2020).
brain diseases (1 paper, 2021). "Almost half of them were involved in axon-related processes (RTN4R, CNTNAP4, ADAM22, PCSK1N, NRXN1), which could indicate that the neurodegenerative mechanisms may be different between these brain diseases." (PMID 33603109, 2021).
PCSK1N also shares sentences with these, for which no sentence is quoted: Anxiety (5 papers); breast cancer (3); infection (3); Parkinsonism (3); frontotemporal dementia (2); Pick disease (2); age-related macular degeneration (1); amyloidosis (1); ataxia-telangiectasia and (1); brain injuries (1); Cognitive impairment (1); colon adenocarcinoma (1); colorectal cancer (1); COVID-19 (1); depression (1); fibromyalgia (1); gastric cancer (1); glaucoma (1); glioblastoma (1); Hypertension (1); intestine infections (1); lung carcinoma (1); migraine (1); myeloma (1); Renal cyst (1); retinal disorder (1); retinitis pigmentosa (1); Salmonella Infections (1); schizophrenia (1).